PLXNC1 (plexin C1)
Description:
Receptor for SEMA7A, for smallpox semaphorin A39R, vaccinia virus semaphorin A39R and for herpesvirus Sema protein. Binding of semaphorins triggers cellular responses leading to the rearrangement of the cytoskeleton and to secretion of IL6 and IL8 (By similarity).
Synonyms: CD232; VESPR; PLXN-C1
Tractability: Small molecule: it has a high-quality binding pocket. Antibody: its Gene Ontology location is reachable by antibodies, with high confidence; UniProt predicts a signal peptide or a membrane-spanning region. PROTAC: ubiquitination databases record sites on it; its protein half-life has been measured.
Gene: Protein-coding gene on chromosome 12 (94,148,577 to 94,307,675, forward strand). Ensembl gene ENSG00000136040.
Subcellular location: Membrane
Subcellular location (Human Protein Atlas): Mitochondria
Pathways (Reactome):
Developmental Biology: Other semaphorin interactions
Gene Ontology:
Molecular function: protein binding; semaphorin receptor activity; signaling receptor binding
Biological process: cell adhesion; negative regulation of cell adhesion; positive regulation of axonogenesis; regulation of cell migration; regulation of cell shape; semaphorin-plexin signaling pathway; synapse assembly; regulation of synapse pruning
Cellular component: membrane; plasma membrane; semaphorin receptor complex; cerebellar climbing fiber to Purkinje cell synapse
Genetic constraint (gnomAD): Loss-of-function variants: 49 observed, 107.46 expected, observed/expected ratio (o/e) 0.46, 90% interval 0.36 to 0.58. The upper end of that interval is the gene's LOEUF score, 0.58, which puts it in group 2 of 6, group 1 being the genes least tolerant of losing a copy. Missense variants: 1,168 observed, 1,462.3 expected, observed/expected ratio (o/e) 0.8, 90% interval 0.76 to 0.84. Synonymous variants: 645 observed, 592.09 expected, observed/expected ratio (o/e) 1.09, 90% interval 1.02 to 1.16.
Homologues: Orthologues: chimpanzee PLXNC1 (99% identical), macaque PLXNC1 (99% identical), dog PLXNC1 (91% identical), mouse Plxnc1 (91% identical), pig PLXNC1 (91% identical), rat Plxnc1 (91% identical), guinea pig PLXNC1 (89% identical), zebrafish plxnc1 (29% identical), Drosophila melanogaster PlexA (26% identical), Drosophila melanogaster PlexB (24% identical), Caenorhabditis elegans plx-1 (23% identical), Caenorhabditis elegans plx-2 (19% identical). Paralogues in human: PLXND1 (32% identical), PLXNB1 (27% identical), PLXNA2 (26% identical), PLXNA1 (26% identical), PLXNB3 (26% identical), PLXNA4 (25% identical), PLXNB2 (25% identical), PLXNA3 (25% identical).
Diseases named in the same sentence as PLXNC1 in open-access papers:
PLXNC1 is named in the same sentence as 41 diseases in open-access papers, as found by Europe PMC text mining. Sharing a sentence is not in itself a finding about the gene and the disease. The quoted sentences say what the papers report.
melanoma (10 papers, 2012 to 2024). A malignant, usually aggressive tumor composed of atypical, neoplastic melanocytes. "A further piece of supporting evidence is found in a mouse model of melanoma, where PlxnC1 expression was positively correlated with Ednrb, suggesting a role in the Ednrb/EDNRB-mediated suppressive effect on melanoma development." (PMID 39001376, 2024). "We showed that PLXNC1 was indeed up-regulated in vemurafenib-resistant SK-Mel28 and 1205Lu melanoma cells." (PMID 39001376, 2024). "PLXNC1 expression was lost in metastatic melanoma as compared to matched primary tumors, and, therefore, PLXNC1 in melanoma is considered to be a tumor suppressor." (PMID 39001376, 2024). "The binding of sema7A to plexin-C1 and β1 integrin receptors stimulates the expression of the Chi3l1 gene, which promotes metastasis of melanoma and breast cancer cells." (PMID 37627074, 2023). "Plexin-C1 expression is downregulated in primary malignant melanoma as compared with melanocytic nevi and is lowest in metastatic melanoma." (PMID 37627074, 2023). "These are EGFR, ERRFI1, IL6, JAK2, PLXNC1, RGL3 which were found to be upregulated and CBL, CDC42, PIK3R3, STAT3, UBE2D2 and YWHAZ which were found to be downregulated; Melanoma has PLXNC1 as upregulated and TGFA as downregulated gene." (PMID 34764329, 2021). "In relation with this finding, an immunohistochemistry study in melanoma patients showed decreased levels of Plexin C1 protein in metastatic cases but its moderate to strong expression in non-metastatic melanoma and nevus tissues." (PMID 30327758, 2018). "Underexpression of plexin receptor C1 (PLXNC1), a receptor characterized as a tumor suppressor in melanoma was observed in late stage and MYCN-amplifying NB in seven cases." (PMID 23106811, 2012). "Furthermore, NRP2, PLXNC1 and PLXNB3 were also positively associated with cell sensitivity to Dabrafenib, which is the treatment for late-stage melanoma and metastatic non-small cell lung cancer with BRAF V600E or V600K mutations." (PMID 32640719, 2020). "In addition, NRP2, PLXNA1, PLXNC1, and PLXNB3 were found to be all positively associated with cell sensitivity to Vemurafenib, which is used for the treatment for late-stage melanoma." (PMID 32640719, 2020). "Tumor suppressive function of NF1 (neurofibromatosis type 1) in several cancer types including melanoma, DAB2IP in prostate cancer, RASAL2 in breast cancer, PLXNC1 (Plexin C1) and RASA2 in melanoma have been described." (PMID 26993606, 2016). "Similarly, in melanoma, SEMA7A/Plexin-C1 engagement inhibits cell migration via inactivation of the cofilin pathway." (PMID 30847405, 2019). "Immunohistochemistry studies revealed that 66% of the metastatic melanoma tissues are devoid of Plexin C1 protein expression, while nontumoral adjacent tissues have modest to high level of Plexin C1." (PMID 30327758, 2018). "Also, Plexin C1 is involved in melanoma progression, its expression is absent in the early stages of the melanoma but occurs in late stages as a pro-survival and anti-apoptotic factor marker and acts via the activation of AKT pathway." (PMID 31681584, 2019).
gastric cancer (6 papers, 2020 to 2025). A primary or metastatic malignant neoplasm involving the stomach. "In stomach cancer, PLXNC1 was significantly associated with M2 macrophages and poor outcome." (PMID 39001376, 2024). "PLXNC1 is reported as an oncogene in liver carcinoma and gastric cancer and also played a part in TC progression." (PMID 34179011, 2021). "Additionally, the natural polyphenol epigallocatechin gallate (EGCG) exerts dual immunomodulatory effects by transcriptionally repressing STAT3, thereby downregulating PLXNC1 expression and reducing exosomal miR-92b-5p levels in gastric cancer cells." (PMID 41229433, 2025). "However, in hepatocellular carcinoma and stomach cancer, PLXNC1 promotes cancer cell proliferation and metastasis, and is associated with overall poorer survival." (PMID 39001376, 2024).
hepatocellular carcinoma (5 papers, 2018 to 2025). A malignant tumor that arises from hepatocytes. "Additionally, plexin-C1 is over-expressed in hepatocellular carcinoma, and its expression is inversely correlated with overall survival." (PMID 37627074, 2023). "The findings were validated in hepatocellular carcinoma (HCC) tumor models in immunodeficient mice, which revealed that cells expressing PLXNC1 were responsive to drug treatment." (PMID 40365104, 2025). "In hepatocellular carcinoma (HCC), plexin-C1 was overexpressed." (PMID 37627074, 2023).
glioma (4 papers, 2018 to 2023). A benign or malignant brain and spinal cord tumor that arises from glial cells (astrocytes, oligodendrocytes, ependymal cells). "LncRNA GAS5, as a tumor suppressor, induces the upregulation of Plexin C1 by decreasing miR-222 levels in human glioma cells, thereby inducing cofilin inactivation and promoting cell migration and invasion." (PMID 35246511, 2022). "On the other hand, cytofluorimetric analysis revealed the presence of integrin beta 1, but not Plexin C1—two major SEMA7A receptors—on glioma stem cells (GSCs)." (PMID 31151295, 2019). "In addition, both Plexin C1 and its positive regulator GAS5, a long non-coding RNA, were downregulated in glioma tissues and cell lines." (PMID 30327758, 2018).
metastatic melanoma (3 papers, 2018 to 2024). A melanoma that has spread from its primary site to another anatomic site. "In metastatic melanoma, there is a significant loss of PLXNC1, which results in an enhanced activation of CFL1 and acquisition of a metastatic phenotype by cancer cells." (PMID 35008571, 2021).
stomach adenocarcinoma (3 papers, 2020 to 2024). "Similarly, PLXNC1, a member of the Plexin family composed of transmembrane domains, was also shown to be significantly associated with M2 macrophages, and indicated poor outcome in stomach adenocarcinoma and acute myeloid leukemia." (PMID 39001376, 2024). "PLXNC1, regulated by IRF5, is an immune-related gene that was significantly associated with M2 macrophages and poor outcome in stomach adenocarcinoma." (PMID 34277610, 2021). "For the rest of the PLXN family members, PLXNA2 was only associated with survival advantage for KIRC and LUAD, and PLXNC1 was only associated with survival disadvantage of LAML and stomach adenocarcinoma (STAD)." (PMID 32640719, 2020).
acute peritonitis (2 papers, 2021 to 2023). "However, when evaluating the local environment during ZyA-induced peritonitis we only found very low expression of PLXNC1 on the intestinal organs (for details)." (PMID 38094294, 2023). "Similarly, in zymosan A (ZyA)- induced peritonitis in mice, genetic inactivation and functional inhibition of PLXNC1 results in reduced peritoneal lavage granulocyte counts, protein content, MPO activity, and cytokine levels (TNF-a, IL-6, MIP-1-a, MIP-2)." (PMID 34012455, 2021). "In investigations of animal models with localized acute inflammation, as in with acute peritonitis, SEMA7A and its receptor PLXNC1, as well as SEMA4A are shown to enhance the inflammatory response." (PMID 34012455, 2021).
liver cancer (2 papers, 2018 to 2020). An epithelial or non-epithelial malignant neoplasm that arises from the liver. "In liver cancer, PLXNC1 marks epithelial phenotype of liver cancer cells and is significantly up-regulated in liver cancer tissues, which suggests the important roles of PLXNC1 in liver cancer." (PMID 32117710, 2020).
metastatic tumors (2 papers, 2020 to 2022). "In a pan-cancer study, the overall expression of PLXNC1 is up-regulated in primary and metastatic tumors and may be associated with a more aggressive cancer phenotype." (PMID 36419120, 2022). "Interestingly, even the genes that showed no differential expression in tumors compared to normal samples also showed significantly increased (NRP2 and PLXNC1) or decreased (PLXNB1 and SEMA3F) expression in metastatic tumors (p < 0.0001)." (PMID 32640719, 2020).
pulmonary fibrosis (2 papers, 2021 to 2024). Chronic progressive interstitial lung disorder characterized by the replacement of the lung tissue by connective tissue, leading to progressive dyspnea, respiratory failure, or right heart failure. "A deficiency of PLXNC1 enhanced the development of pulmonary fibrosis and could be ameliorated when PLXNC1 was reconstituted." (PMID 39169397, 2024). "The capacity of PLXNC1 to serve as a stop signal is also shown in macrophages during the development of pulmonary fibrosis." (PMID 39169397, 2024).
pulpitis (2 papers, 2023). Inflammation of the dental pulp. "built a ceRNA network based on differentially expressed data of pulpitis, containing lncRNA PVT1, hsa-miR-455-5p, and 2 mRNAs (SOCS3 and PLXNC1)." (PMID 37275855, 2023). "In the instance of pulpitis, the upregulation of PVT1 promotes inflammation and cytokine and chemokine production, while diminishing the expression of miR-455-5p and indirectly raising the expression of SOCS3 and PLXNC1 and the cytokine cascade." (PMID 36890871, 2023).
vasculitis (2 papers, 2024 to 2025). "A recent report showed that Sema7A contributes to the progression of KD vasculitis by promoting endothelial permeability and inflammation through a Plexin C1- and Integrin β1-dependent pathway." (PMID 39857904, 2025). "Sema7A is involved in the progression of KD vasculitis by promoting endothelial permeability and inflammation through a plexin C1 and integrin β1-dependent pathway." (PMID 38678170, 2024). "Based on the KD cell model with upregulated plexin C1 and integrin β1 and the important role of inflammatory activation of vascular endothelial cells in KD vasculitis, we explored the action of Sema7A on inflammation in HCAECs." (PMID 38678170, 2024). "Our findings suggest that the Sema7A/plexin C1/integrin β1 axis is involved in the progression of KD, and Sema7A may serve as a novel prognostic and therapeutic candidate for KD vasculitis." (PMID 38678170, 2024).
Cirrhosis (1 paper, 2018). A chronic disorder of the liver in which liver tissue becomes scarred and is partially replaced by regenerative nodules and fibrotic tissue resulting in loss of liver function. "In correlation analyses, we could not detect any association between Plexin C1 intensity and clinicopathological parameters such as age, sex, stage, cirrhosis background, and survival of patients." (PMID 30327758, 2018).
edema (1 paper, 2021). An abnormal accumulation of fluid beneath the skin, or in one or more cavities of the body. "In the study of acute lung injury caused by seawater aspiration, Sema7a contributed to seawater-induced pulmonary edema and inflammation via the Plexin C1/β1 integrin pathway." (PMID 34007409, 2021).
leukemia (1 paper, 2017). A malignant (clonal) hematologic disorder, involving hematopoietic stem cells and characterized by the presence of primitive or atypical myeloid or lymphoid cells in the bone marrow and the blood. "The angiogenesis is another process getting disorder in cancerous states (PLXNC1 and PCDH9 genes in the list of leukemia)." (PMID 29563929, 2017). "Also, key genes of leukemia data set were BAG4, ANKHD1-EIF4EBP3, PLXNC1, and PCDH9 genes, and the accuracy and precision were 100 and 95.24, respectively." (PMID 29563929, 2017). "The process of contact and intracellular connections and cellular migration (PLXNC1 and PCDH9 genes in leukemia) and other processes such as activating EGFR and SMAD pathways were the other processes that selected genes in this project were involved to control and regulate the processes." (PMID 29563929, 2017).
nonsmall cell lung cancer (1 paper, 2025). "In nonsmall cell lung cancer (NSCLC), higher Plexin C1 expression compared to healthy lung epithelial cells has been observed, and the interaction of Plexin C1 with its ligand SEMA7A promotes cell migration." (PMID 40365104, 2025).
papillary thyroid cancer (1 paper, 2020). "In papillary thyroid cancer (PTC), miR-4500 functions as a tumor suppressor by decreasing PLXNC1 expression, and knockdown of PLXNC1 represses colony formation, proliferation, invasiveness, and enhances apoptosis in PTC cells." (PMID 32117710, 2020).
Sepsis (1 paper, 2024). Sepsis is defined as life-threatening organ dysfunction caused by a dysregulated host response to infection. "We demonstrate how PLXNC1 significantly regulates the immune response to intracellular LPS and might be a target for the suppression of sepsis-associated secondary organ injury in the future." (PMID 39169397, 2024). "To evaluate a potential influence of PLXNC1 on the inflammatory processes during sepsis, we subjected PLXNC1-/- mice to polymicrobial sepsis via CLP." (PMID 39169397, 2024). "Future work should focus on a possible role of the described axis, using PLXNC1 to reduce the detrimental effects of hyperinflammation during sepsis." (PMID 39169397, 2024). "Twenty-four hours after sepsis induction, levels of the proinflammatory cytokines TNF-α, IL-6, and KC were significantly higher in the peritoneal lavage fluid of PLXNC1-/- mice, suggesting an inflammation-suppressing function for PLXNC1 in vivo during sepsis." (PMID 39169397, 2024). "Control of caspase-11 (caspase 4/-5 in humans) is proven to be a valuable target to interfere with sepsis induced damage, and we show that PLXNC1 holds the potential to control this activity." (PMID 39169397, 2024). "Taken together, our in vivo findings suggest that SL4c-d is a potential therapeutic tool for sepsis and might help suppress inflammatory damage through a PLXNC1-dependent pathway." (PMID 39169397, 2024). "Furthermore, we demonstrate here that the activation of plexin C1 by ligand-binding during murine polymicrobial sepsis ameliorates inflammatory response and improves survival." (PMID 39169397, 2024). "Notably, administration of SL4c-d—peptide ligand of PLXNC1—reduces the inflammatory response during CLP-induced sepsis and improves survival." (PMID 39169397, 2024). "In addition, we aimed to identify a therapeutic potential of PLXNC1 during sepsis." (PMID 39169397, 2024). "The absence of PLXNC1 results in excessive inflammation marked by increased cytokine release, increased secondary organ injury and reduced sepsis survival in a murine sepsis model induced by CLP." (PMID 39169397, 2024). "We employed a murine model of sepsis via cecal ligation and binding (CLP), using PLXNC1-/- mice and littermate controls, and additionally transfected murine bone-marrow-derived macrophages (BMDMs) from both genotypes with LPS to achieve activation of the noncanonical inflammasome ex vivo." (PMID 39169397, 2024). "In our in vivo model of polymicrobial sepsis, the absence of PLXNC1 resulted in a more severe inflammatory immune response, markedly with higher levels of IL-1β and IL-18, the hallmark cytokines of inflammasome activity." (PMID 39169397, 2024).
systemic vasculitis (1 paper, 2025). "This increased expression of receptor Plexin C1 has also been identified in paediatric systemic vasculitis." (PMID 40114253, 2025).